Y_RNA (Y RNA )
Gene: Miscellaneous RNA gene on chromosome 1 (28,881,726 to 28,881,835, reverse strand). Ensembl gene ENSG00000199756.
Homologues: Paralogues in human: RNY1 (83% identical), Y_RNA (82% identical), Y_RNA (81% identical), RNY1P7 (80% identical), Y_RNA (80% identical), Y_RNA (79% identical), Y_RNA (78% identical), RNY1P9 (77% identical), Y_RNA (77% identical), RNY1P16 (76% identical), RNY1P5 (76% identical), Y_RNA (76% identical), and 91 more.